MTG2 (mitochondrial ribosome associated GTPase 2)
Description:
Plays a role in the regulation of the mitochondrial ribosome assembly and of translational activity. Displays GTPase activity. Involved in the ribosome maturation process.
Synonyms: ObgH1; GTPBP5; FLJ10741; dJ1005F21.2
Tractability: Small molecule: a structure with a bound ligand is known. Antibody: UniProt places it where antibodies can reach, with medium confidence. PROTAC: ubiquitination databases record sites on it; its protein half-life has been measured.
Gene: Protein-coding gene on chromosome 20 (62,183,025 to 62,203,568, forward strand). Ensembl gene ENSG00000101181.
Subcellular location: Mitochondrion; Mitochondrion inner membrane
Gene Ontology:
Molecular function: GTPase activity; GTP binding; magnesium ion binding
Biological process: mitochondrial large ribosomal subunit assembly; regulation of mitochondrial translation; regulation of respiratory system process
Cellular component: mitochondrial inner membrane; mitochondrial matrix; mitochondrial ribosome; mitochondrion
Genetic constraint (gnomAD): Loss-of-function variants: 22 observed, 29.5 expected, observed/expected ratio (o/e) 0.75, 90% interval 0.53 to 1.07. The upper end of that interval is the gene's LOEUF score, 1.07, which puts it in group 4 of 6, group 1 being the genes least tolerant of losing a copy. Missense variants: 535 observed, 573.37 expected, observed/expected ratio (o/e) 0.93, 90% interval 0.87 to 1. Synonymous variants: 259 observed, 262.25 expected, observed/expected ratio (o/e) 0.99, 90% interval 0.89 to 1.1.
Homologues: Orthologues: chimpanzee MTG2 (99% identical), macaque MTG2 (93% identical), rat Mtg2 (82% identical), mouse Mtg2 (80% identical), guinea pig MTG2 (79% identical), rabbit MTG2 (78% identical), pig MTG2 (77% identical), dog MTG2 (73% identical), tropical clawed frog mtg2 (62% identical), zebrafish mtg2 (55% identical), Caenorhabditis elegans M01E5.2 (41% identical), Drosophila melanogaster CG13390 (38% identical). Paralogues in human: GTPBP10 (34% identical), DRG1 (19% identical), GTPBP4 (18% identical), DRG2 (15% identical).
Diseases named in the same sentence as MTG2 in open-access papers:
MTG2 is named in the same sentence as 7 diseases in open-access papers, as found by Europe PMC text mining. Sharing a sentence is not in itself a finding about the gene and the disease. The quoted sentences say what the papers report.
geographic atrophy (1 paper, 2022). "The identification of eQTL in genes encoding mitochondrial proteins and respiratory complexes, such as MTG2 and DPYSL4 further suggests that variations in mitochondrial activities in the RPE might be at play in the progression of geographic atrophy." (PMID 35882847, 2022).
osteosarcoma (1 paper, 2015). A usually aggressive malignant bone-forming mesenchymal neoplasm, predominantly affecting adolescents and young adults. "Across all Ewing and osteosarcoma cell lines eleven genes were found to be either significantly (P < 0.05, Bonferroni correction) repressed (KIF20A, IDH1, SCD, GPSM2, EIF2AK4, HIBCH) or induced (STK19, DNAJC24, MTG2, FAM175B, CYB5D1) following non DNA-damaging XI-006 treatment (0.5 μM)." (PMID 26095524, 2015).
cancer (2 papers, 2020 to 2025). A tumor composed of atypical neoplastic, often pleomorphic cells that invade other tissues. "The effects of non-coding mutations on MTG2 transcription have been summarized in various cancer cell lines, and increased expression of DAAM1 leads to aggressive cell migration." (PMID 40544380, 2025).
tumor (1 paper, 2025). "MTG2 (myeloid translocation gene 2) functions as a transcriptional regulator and is involved in chromatin remodeling and gene expression regulation, playing established roles in hematopoietic development and tumor suppression." (PMID 40544380, 2025).
MTG2 also shares sentences with these, for which no sentence is quoted: esophageal cancer (1 paper); fibrosis (1); mitochondrial disease (1).